GSDMA (gasdermin A)
Description:
[Gasdermin-A]: This form constitutes the precursor of the pore-forming protein and acts as a sensor of infection: upon infection by S.pyogenes, specifically cleaved by S.pyogenes effector protein SpeB in epithelial cells, releasing the N-terminal moiety (Gasdermin-A, N-terminal) that binds to membranes and forms pores, triggering pyroptosis. [Gasdermin-A, N-terminal]: Pore-forming protein that causes membrane permeabilization and pyroptosis. Released upon cleavage by S.pyogenes effector protein SpeB, and binds to membrane inner leaflet lipids. Homooligomerizes within the membrane and forms pores of 10-15 nanometers (nm) of inner diameter, triggering pyroptosis. Pyroptosis triggers the elimination of the infected skin cell, depriving the pathogen of its protective niche, while inducing an inflammatory response. This ultimately prevents bacterial penetration of the epithelial barrier and a subsequent systemic dissemination of the pathogen. Binds to cardiolipin and other acidic phospholipids, such as phosphatidylserine, which mediate its targeting to the inner leaflet membrane.
Synonyms: GSDM; GSDM1; FKSG9; FLJ39120
Tractability: Antibody: UniProt places it where antibodies can reach, with high confidence; UniProt predicts a signal peptide or a membrane-spanning region; its Gene Ontology location is reachable by antibodies, with medium confidence; the Human Protein Atlas places it where antibodies can reach.
Gene: Protein-coding gene on chromosome 17 (39,953,263 to 39,977,768, forward strand). Ensembl gene ENSG00000167914.
Subcellular location: Cytoplasm, perinuclear region (Gasdermin-A); Cytoplasm, cytosol; Cell membrane (Gasdermin-A, N-terminal)
Subcellular location (Human Protein Atlas): Cytosol; Plasma membrane; Nuclear bodies; Nucleoplasm
Gene Ontology:
Molecular function: protein binding; phosphatidylinositol-4,5-bisphosphate binding; phosphatidylinositol-4-phosphate binding; phosphatidylserine binding
Biological process: defense response to bacterium; pyroptotic inflammatory response
Cellular component: cytosol; nuclear body; nucleoplasm; perinuclear region of cytoplasm; plasma membrane
Genetic constraint (gnomAD): Loss-of-function variants: 37 observed, 39.22 expected, observed/expected ratio (o/e) 0.94, 90% interval 0.73 to 1.24. The upper end of that interval is the gene's LOEUF score, 1.24, which puts it in group 5 of 6, group 1 being the genes least tolerant of losing a copy. Missense variants: 461 observed, 466.36 expected, observed/expected ratio (o/e) 0.99, 90% interval 0.92 to 1.07. Synonymous variants: 181 observed, 194.57 expected, observed/expected ratio (o/e) 0.93, 90% interval 0.82 to 1.05.
Homologues: Orthologues: chimpanzee GSDMA (99% identical), macaque GSDMA (97% identical), rabbit GSDMA (91% identical), pig GSDMA (90% identical), dog GSDMA (89% identical), mouse Gsdma (89% identical), rat Gsdma (87% identical), guinea pig GSDMA (86% identical), mouse Gsdma3 (77% identical), mouse Gsdma2 (76% identical), zebrafish pjvk (16% identical). Paralogues in human: GSDMD (33% identical), GSDMC (31% identical), GSDMB (27% identical), PJVK (14% identical).
Diseases named in the same sentence as GSDMA in open-access papers:
GSDMA is named in the same sentence as 72 diseases in open-access papers, as found by Europe PMC text mining. Sharing a sentence is not in itself a finding about the gene and the disease. The quoted sentences say what the papers report.
asthma (39 papers, 2011 to 2025). "The human 17q12‐21 gene locus is associated with GSDMA and asthma, leading to changes in the expression levels of the GSDMA gene in CD4 T cells of asthma patients and affecting its methylation levels." (PMID 40273335, 2025). "In contrast, a number of prior genome-wide association studies have demonstrated a correlation between the polymorphisms in Gasdermin A and B and the susceptibility to adult and paediatric asthma in various populations." (PMID 40104184, 2024). "The interplay between DNA methylation and GSDMA expression was found related to an individual’s susceptibility to asthma." (PMID 36248872, 2022). "While our study provides evidence for African-specific variants that modify the genetic risk attributed to the 17q12-q21 childhood-onset asthma locus by increasing expression of GSDMA, there are limitations." (PMID 36175932, 2022). "Our studies revealed nine novel African-specific common variants, enriched on a high-risk asthma haplotype, which regulated the expression of GSDMA in airway epithelial cells and were associated with features of severe asthma." (PMID 36175932, 2022). "GSDMA has also been associated with susceptibility to asthma, and macrophage transcriptome analysis has revealed that GSDMA is associated with the pathogenesis of sclerosis and inflammatory bowel disease." (PMID 35647057, 2022). "Asthma‐associated polymorphisms at the locus 17q12‐21 mediate the expression and methylation of the GSDMA gene in CD4+ T cells." (PMID 34459122, 2021). "A study of Korean children revealed that the susceptibility to asthma and intermediate asthma phenotypes, such as elevated IgE and bronchial hyperresponsiveness, is associated with GG of GSDMA (rs7212938) and TT of GSDMB (rs7216389)." (PMID 34858408, 2021). "In turn, the GSDMA polymorphism (rs3859192 on chr17q21) is strongly linked with asthma susceptibility and intermediate phenotypes in asthma." (PMID 34459122, 2021). "SNPs extending both proximal (including PGAP3 and ERBB2) and distal (including GSDMA) to the core region show less LD with those in the core region and have been implicated as potentially independent asthma risk loci." (PMID 34629083, 2021). "Lower DNA methylation at promoter regions of GSDMA in peripheral blood cells of asthmatic individuals and in lymphoblastoid cell lines correspond to asthma-predisposing alleles." (PMID 34858408, 2021). "In the first genome wide association study for asthma published in 2007, it was reported that the ORMDL3/GSDMA locus at chromosome 17q12 was specifically associated with childhood onset asthma." (PMID 32603359, 2020). "Using publicly available mouse developmental gene expression data (GSE21052) we also confirmed the correlation of miR-15a miR-15b with the asthma susceptibility chromosome 17q locus including GSDMA (R = −0.56923) and ORMDL3 (R = +0.6044)." (PMID 33291534, 2020). "The strongest eQTL SNP on 17q was rs3859192 located in intron 6 of GSDMA, which is associated with asthma." (PMID 30847004, 2019). "Our previous work demonstrated that lower methylation levels of certain CGs in the ZPBP2 and GSDMA promoters in peripheral blood cells are associated with asthma in females." (PMID 28241063, 2017). "GSDMA has also been linked with airway hyperresponsiveness; polymorphisms in GSDMA are associated with asthma susceptibility, and risk alleles on asthma-associated locus are linked with increased GSDMA gene expression." (PMID 26100518, 2015). "The sub-network around GSDMA is significantly enriched for canonical genes (P = 0.005) suggesting that GSDMA is the most likely driver behind the asthma association on 17q21." (PMID 23209423, 2012). "Further support for GSDMA as an asthma susceptibility gene is our observation that GSDMA is robustly expressed in human airway epithelium." (PMID 23209423, 2012).
asthma (continued). "The strongest eSNP in the 17q asthma susceptibility locus was rs3859192 located in intron 6 of the GSDMA gene governing the expression levels of this gene (P = 3.55×10−151)." (PMID 23209423, 2012). "That is, the common GSDMA alleles associated with reduced risk of asthma in the CREW African American cohort were associated with reduced GSDMA expression in lung tissue, in nearly all tissues in the Genotype-Tissue Expression consortium, and in upper airway epithelial cells in our study." (PMID 36175932, 2022). "Our results suggested that the novel variants are associated with increased expression of GSDMA via long-range chromatin interactions and are associated with a type 2 (T2) low asthma phenotype in African American children and asthma severity in African American adults." (PMID 36175932, 2022). "Second, airway epithelial cell expression of GSDMA was too low to determine whether the combined expression levels of both genes were associated with greater risk or severity of asthma compared to expression levels of each gene separately." (PMID 36175932, 2022). "Moreover, the interplay between DNA methylation and GSDMA expression plays a crucial role in an individual’s predisposition to asthma." (PMID 34858408, 2021). "This genomic region consists of a number of genes, including ORMDL3, GSDMB, IKZF3, ZPBP2, and GSDMA that are in LD and may either be individually or jointly responsible for the asthma association." (PMID 30541564, 2018). "The unweighted hypothesis testing claimed 6 SNPs to be significant, all on chromosome 17, including 2 asthma-associated SNPs (rs3894194 with GSDMA, and rs7216389 with ORDML3) that have been reported previously." (PMID 23755072, 2013). "However, increased expression of GSDMA was found in cord blood lymphocytes of individuals that carry the asthma-associated 17q12-q21 alleles, suggesting that GSDMA cannot be excluded from the list of putative asthma genes." (PMID 22271045, 2012). "However, the most compelling eQTL on 17q21 was observed in the association between the asthma susceptibility SNP (rs3859192 – p = 1.11−12 for association with asthma) and the level of expression of GSDMA (P = 3.55×10−151)." (PMID 23209423, 2012). "Regulatory variants for GSDMA identified in the lung may regulate a different gene(s) in another relevant tissue or cell-type for asthma." (PMID 23209423, 2012). "Thus our data strongly suggest that the SNPs across this whole locus are associated with asthma because they modulate GSDMA expression in the lung, clearly showing the value of our lung eQTL dataset to refine previous GWAS hits for asthma." (PMID 23209423, 2012). "A study identified that only GSDMB and maybe GSDMA members of the GSDM family are linked to asthma." (PMID 40104184, 2024). "Therefore, we could not determine whether the novel alleles by themselves contribute to asthma risk or whether increased expression of GSDMA modifies risk only in the presence of increased GSDMB expression." (PMID 36175932, 2022). "While GSDMA is plausibly involved in asthma pathogenesis through immune inflammasome and mitochondrial reactive oxygen species generation pathways, it is also a precursor of pore-forming proteins and acts as a sensor of infection." (PMID 40867500, 2025). "Among the protein-coding genes causally associated with unspecified asthma in lung and blood, seven are within the 17q12-21 locus (i.e., PGAP3, IKZF3, GSDMB, ORMDL3, GSDMA, MED24, and CASC3)." (PMID 39628479, 2024). "The asthma L-GRN includes HLA genes and other genes previously reported to be associated with asthma (e.g., PRKCQ, GSDMA, and GSDMB)." (PMID 37680636, 2023). "In the STEPS study, asthma risk alleles in IKZF3, GSDMA, GSDMB, ZPBP2, and ORMDL3 genes were associated with a higher risk of a wheezing illness (all P values ≤.02)." (PMID 36967681, 2023). "GSDMA is expressed in epithelial cells and has been linked to autoimmune diseases and cancer.GSDMB is reported to be associated with asthma and colitis." (PMID 35634294, 2022).
asthma (continued). "The levels of DNA methylation and gene expression in patients with asthma indicate that GSDMA is a key factor in the disease pathogenesis." (PMID 34858408, 2021). "Previously, a series of genome‐wide association studies (GWAS) indicated that GSDMA and GSDMB polymorphisms are associated with asthma." (PMID 34590363, 2021). "Analogous to GSDMA, GSDMB is also linked to childhood‐onset asthma, while GSDMB (rs9303277) in CD4+ T cells is an SSc‐associated susceptibility locus." (PMID 34459122, 2021). "Associations have been shown between GSDMA gene and asthma and, between GSDMB gene and asthma or early childhood asthma with severe exacerbations." (PMID 33133517, 2020). "Although the region covering the ORMDL3, GSDMA and GSDMB genes is the most replicated one, the keratin (KRT) cluster has also been shown to be associated with asthma in a previous GWAS study." (PMID 26672748, 2015). "A recent study also showed that asthma risk alleles on 17q21 were associated with increased ORMDL3 and GSDMA gene expression and elevated IL-17 secretion in cord blood mononuclear cells." (PMID 23209423, 2012). "Further investigation is needed to determine whether the same GSDMA-mediated immune inflammasome and ROS pathways are involved in both childhood asthma development and RSV infection severity." (PMID 40867500, 2025). "Our study identified an association between SNP (rs8069202) at the 17q12-q21 asthma risk locus, near the GSDMA gene, and increased RSV viral load, as well as a non-significant trend with increased RSV LRTI risk." (PMID 40867500, 2025). "The asthma risk alleles in CDHR3, GSDMA, and GSDMB were associated with an increased rate of ARIs (for CDHR3, incidence rate ratio [IRR], 1.06; 95% confidence interval [CI], 1.01–1.12; P = .02), and risk allele in CDHR3 gene with rhinovirus infections (IRR, 1.10; 95% CI, 1.01–1.20, P = .03)." (PMID 36967681, 2023). "In addition, GSDMA has been reported to carry rs3894194, which is rich in gene, and regarded as being linked with certain immune diseases such as IBD, asthma and rheumatoid arthritis (RA)." (PMID 35720396, 2022). "Thus far, it has been reported that GSDMA is involved in skin inflammation, epidermal differentiation, and the development of asthma." (PMID 36003332, 2022). "In childhood asthma, there was a significant correlation of GSDMA (rs7212938) with it as GSDMA may drives the frequency of asthma." (PMID 35720396, 2022). "GSDMA is along with GSDMB and ORMDL3 part of the complex 17q21.1 locus, more research is needed to understand the specific interactions of variants in this region and their role in asthma pathobiology." (PMID 30373671, 2018). "Furthermore, it was recently reported that polymorphisms with GSDMA and GSDMB loci are associated with asthma, atopy and intermediate phenotypes such as elevated immunoglobulin E." (PMID 23979942, 2013). "Review of previous T1D genome-wide association results revealed that four (human leucocyte antigen (HLA), gasdermin B/ORM1 (Saccharomyces cerevisiae)-like/gasdermin B/, GSDMB/ORMDL3/GSDMA and IL2RB) of ten loci recently reported to be associated with asthma were associated with T1D (p≤0.005)." (PMID 22069270, 2011). "It is important to note, however, that while the current experimental evidence excludes IKZF3 (IKZF3 is not affected by the haplotype effect in LCLs or T lymphocytes), it is not sufficient for ruling out ZPBP2, GSDMB or GSDMA as contributors to predisposition to asthma." (PMID 22271045, 2012). "However, the relationship between GSDMA-induced pyroptosis and asthma remains unclear." (PMID 36248872, 2022). "We identified three genes (GSDMA in chr17, GSDMB in chr17, and ORMDL3 in chr17) with statistically independent genetic effects from all of the shared TWAS genes between asthma and HF." (PMID 35126453, 2021). "GSDMA, GSDMB, and ORMDL3 are statistically independent genetic effects from all shared TWAS genes between asthma and HF." (PMID 35126453, 2021).
asthma (continued). "The association of a SNP in GSDMA with RSV viral load and RSV infection severity suggests that GSDMA may be contributing to both severe RSV infection and asthma development." (PMID 40867500, 2025). "However, the mechanism whereby GSDMA and GSDMB promote the onset of asthma is largely unknown." (PMID 34590363, 2021).
gastric cancer (21 papers, 2009 to 2024). A primary or metastatic malignant neoplasm involving the stomach. "This pathway is associated with the apoptosis of gastric pit cells, as GSDMA is frequently suppressed in esophageal and gastric cancers." (PMID 34858408, 2021). "GSDMA is expressed in the upper gastrointestinal tract and is strongly linked with asthma susceptibility, but its expression is frequently silenced in gastric cancer, suggesting the potential tumor suppressor role in gastrointestinal cancer." (PMID 39062587, 2024). "GSDMA is not only inhibited in esophageal cancer and gastric cancer cells, but it has been found that this mechanism can also induce cell death by upregulating the expression of GSDMA through the transcription factor LMO1." (PMID 37561524, 2023). "It has been reported that while GSDMA is silenced in gastric cancer, GSDMB is overexpressed in several types of cancers (e.g., breast and gastric cancers)." (PMID 36003332, 2022). "Although this observation unveils a possible tumor suppressor role for GSDMA in gastric cancer, its biological significance is yet to be revealed." (PMID 35844522, 2022). "GSDMA is expressed in epithelial cells within the gastrointestinal tract while frequently silenced in primary gastric cancers and in gastric cancer cell lines." (PMID 36505474, 2022). "The expression of GSDMA was significantly increased in the skin and gut, however, it was depleted in gastric cancer." (PMID 35211500, 2022). "For example, GSDMA is expressed at a lower level in human esophageal and gastric cancers than in normal tissue." (PMID 35844522, 2022). "Human GSDMA is expressed in the stomach and skin but is silenced in gastric cancer tissues and cell lines." (PMID 34910689, 2021). "GSDMA was up-regulated by TGFβ and then triggered cell death in the gastric epithelium pit cells, indicating it acts as a tumor suppressor gene in gastric cancer." (PMID 34910689, 2021). "GSDMA was suppressed in esophageal and gastric cancer cells and TGF-b can upregulate GSDMA through the transcription factor LMO1 to induce cell death." (PMID 34778452, 2021). "Secondly, GSDMA expression appears silenced in primary gastric cancers and gastric cancer cell lines." (PMID 33033617, 2020). "GSDMA is frequently silenced in gastric cancer cell lines and has been reported to induce apoptosis when overexpressed in gastric cancer cells." (PMID 26100518, 2015). "Human GASDERMIN A (GSDMA) is frequently silenced in gastric cancer cell lines and its overexpression has been reported to induce apoptosis." (PMID 26100518, 2015). "One example is a potential tumor suppressive gene, GSDMA(NM_178171.4), is localized in a chromosomal region amplified in gastric cancer cells." (PMID 19688090, 2009). "Human GSDMA is relatively widely expressed, not only in the stomach and skin, but also in the pancreas esophagus and mammary gland, and it is frequently silenced in gastric cancer (GC) tissues and cells." (PMID 37125240, 2023). "In addition, GSDMA was identified as a tumor suppressor gene in gastric cancer, whereas GSDMB was observed to be overexpressed and exhibited oncogenic properties." (PMID 37950289, 2023). "Studies have reported that GSDMA may be a tumor suppressor gene, which is generally suppressed in esophageal squamous cell carcinoma and gastric cancer." (PMID 36244998, 2022). "GSDMA is frequently silenced in gastric cancers, indicating that GSDMA might function as a regulator of tumor suppression." (PMID 34298833, 2021). "Therefore, restoring GSDMA expression in gastric cancer cells may be an effective strategy for gastric cancer treatment." (PMID 38066523, 2023). "In gastric cancer, pyroptosis-related genes such as GSDMA, GSDMB, and GSDMC were revealed to be abnormally expressed in GC and associated with tumor progression." (PMID 35198013, 2022). "Moreover, low expression levels of the GSDMA protein have been found in gastric cancers." (PMID 36003332, 2022).